GDF15 (growth differentiation factor 15)
Diseases named in the same sentence as GDF15 in open-access papers (continued):
Sharing a sentence is not in itself a finding about the gene and the disease.
metabolic disorders (continued). "GDF15 is known to play a key role in various pathological conditions including CKD, metabolic disorders as well as sterile and infectious inflammation." (PMID 32375259, 2020). "FGF21 and GDF15 act synergistically to maintain glucose homeostasis and promote resistance to DIO in mice lacking OPA1 in BAT, highlighting the potential of combined therapies using FGF21 and GDF15 for the treatment of metabolic disorders." (PMID 40897647, 2025). "The lack of large trials studying GDF-15 in various cardiovascular and metabolic disorders limits the generalizability of the findings of this article." (PMID 39781722, 2025). "GDF-15 activates GFRAL, influencing metabolism and insulin sensitivity, and may be involved in the development of metabolic disorders, oxidative stress, and inflammation." (PMID 41019919, 2025). "Therefore, our findings provide a new insight regarding the protective role of endogenous GDF15 in NASH and suggest an innovative therapeutic strategy for treatment of NASH or related metabolic disorders." (PMID 29717162, 2018). "The role of GDF15 and its only known hindbrain-restricted receptor GFRAL has been extensively studied in the past years due to its relevance in the control of energy homeostasis and, thereby, being a potential therapeutic target in the control of metabolic diseases such as obesity." (PMID 39505926, 2024). "Furthermore, recombinant GDF15 or GDF15 overexpression ameliorated NASH and related metabolic disorders in mice by alleviating hepatic inflammatory response and modulating lipid metabolism and β-oxidation of fatty acids, which was independently of reduction in body mass." (PMID 37180779, 2023). "Although both parameters (possibly GDF-15 superior to FGF-21) are considered capable of distinguishing patients with mitochondrial diseases from those without, serum concentrations of both molecules are likely to be significantly affected by vascular and metabolic diseases." (PMID 34572118, 2021). "Furthermore, the ability of pGSN to identify young MD patients warrants further research to confirm its potential utility in pediatric patient series, where GDF15 and FGF21 have been shown to be less relevant in differentiating multisystemic mitochondrial disorders from other metabolic diseases." (PMID 34203775, 2021). "Furthermore, whilst a growing body of evidence suggests that GDF-15 may have a pro-fibrogenic role within the liver, others have found GDF-15 to be protective and to ameliorate NASH and other metabolic disorders in mice." (PMID 34663793, 2021). "Combined, these data may suggest a role of GDF15 in the regulation of survival and aging‐related metabolic diseases through a peripheral mechanism independent of GFRAL." (PMID 32691494, 2020).
mitochondrial disease (82 papers, 2016 to 2025). "GDF15 serves as a valuable diagnostic marker for mitochondrial diseases indicating its potential as a biomarker for mitochondrial dysfunction." (PMID 39904253, 2025). "Early or childhood onset of Thymidine Kinase 2 Deficiency, a mitochondrial disease, demonstrated 30‐fold higher GDF15 levels compared to controls, with improvement in clinical outcomes and decreases in GDF15 after treatment with oral deoxynucleosides." (PMID 40019842, 2025). "Mitochondrial diseases are caused by mutations in mitochondrial DNA (mtDNA) and mitochondrial genes and show consistent upregulation of GDF15." (PMID 39737171, 2024). "Another proposed mechanism is mitochondrial dysfunction as circulating GDF-15 levels are considered a reliable diagnostic marker for mitochondrial diseases." (PMID 38791028, 2024). "Due to a firm association of the cytokine with mitochondrial dysfunction, GDF-15 blood levels are now a well-established diagnostic biomarker for mitochondrial diseases." (PMID 36361969, 2022). "Additional studies are needed to clarify the origin and the role of GDF15 in mitochondrial diseases in relation to the pathogenic mechanisms and disease progression." (PMID 34445593, 2021). "GDF15 is a useful diagnostic marker for mitochondrial diseases, which are inherited disorders caused by mitochondrial or nuclear genomic mutations, leading to impaired energy production." (PMID 34445593, 2021). "In the past years, serum FGF21 and serum GDF15 have emerged as two promising diagnostic biomarkers for mitochondrial diseases." (PMID 32397676, 2020). "We previously demonstrated that GDF-15 is a valuable circulating diagnostic biomarker for mitochondrial diseases including mitochondrial DNA depletion and deletion syndromes, MELAS and KSS14–16." (PMID 32572108, 2020). "We identified GDF15 as a potential diagnostic biomarker for mitochondrial diseases by a gene expression study in TK2-deficient human skeletal muscles." (PMID 32397676, 2020). "In different studies, a decreased mitochondrial function has been found in aged tissues and cells, and in studies of mitochondrial diseases caused by impaired respiratory chain function due to genetic mutations, the levels of GDF15 have been found to be elevated in animal models and patients." (PMID 36978899, 2023). "The results of our study demonstrate that GDF-15 may help distinguish which patients have an underlying mitochondrial disease in the context of a nearly normal neurologic examination and symptoms that may be confused with those of patients with CFS." (PMID 36983435, 2023). "However, as briefly mentioned before, GDF15 is associated with mitochondrial dysfunction and has been recently proposed as a biomarker for mitochondrial diseases." (PMID 36698863, 2022). "Recently, serum GDF15 levels have been associated with mitochondrial diseases." (PMID 35721026, 2022). "Considering that the primary cause of mitochondrial diseases is mitochondrial dysfunction, the level of GDF15 in the blood might reflect mitochondrial function in patients, and could, thus, be a suitable marker for mitochondrial dysfunction." (PMID 34445593, 2021). "Yet, this observation agrees with FGF21 being related to muscular system presentation, while GDF15 may be linked to more generalized mitochondrial disease and indicative of disease severity and/or progression." (PMID 34972147, 2021). "• FGF21/GDF15 efficiently identifies mitochondrial diseases due to mutations in tRNA genes." (PMID 32851462, 2020). "Recently, Gdf15 has been shown to be a novel diagnostic marker for mitochondrial diseases." (PMID 33165592, 2020). "GDF15 may be adopted as a novel diagnostic biomarker of mitochondrial diseases." (PMID 34445593, 2021). "Mitochondrial stress also influences FGF‐21 and GDF‐15 production, both biomarkers of mitochondrial diseases." (PMID 41496770, 2025).
mitochondrial disease (continued). "GDF-15, for instance, has been identified as a promising candidate biomarker for gynecological tumors, digestive system tumors, and mitochondrial diseases in several meta-analyses." (PMID 40371061, 2025). "Our search yielded five studies comparing children with mitochondrial disease, all showing significantly increased GDF15 levels compared to healthy controls." (PMID 40019842, 2025). "On the other hand,the direct relationship between GDF15 and mitochondrial DNA (mtDNA) copy number is also not well-established in current scientific literature.Recent studies have suggested a potential role for GDF15 as a biomarker for mitochondrial diseases." (PMID 39904253, 2025). "The laboratory findings emphasize the potential use of GDF-15 as an important biomarker for children with mitochondrial disease and SLSMDS." (PMID 40760494, 2025). "Compared to a wide variety of other inherited disorders, patients with mitochondrial disease were found to have higher GDF15 levels, highest in mitochondrial hepatopathy." (PMID 40019842, 2025). "GDF-15 is listed as a biomarker for mitochondrial diseases and is considered a useful endpoint for future in vivo evaluation." (PMID 38773300, 2024). "FGF21 and GDF15 are well-known mitochondrial biomarkers that showed remarkable elevations in mitochondrial diseases, respectively." (PMID 39124668, 2024). "Across paediatric and adult cases, blood levels of GDF15 were elevated in mitochondrial disease patients compared to their healthy counterparts." (PMID 39737171, 2024). "First, we observed that the mitochondrial disease marker GDF15 was largely undetectable in the media of young, healthy fibroblasts, but increased progressively across the cellular lifespan." (PMID 36635485, 2023). "The usefulness of GDF-15 levels for diagnosing patients with mitochondrial disease, particularly in cases with skeletal muscle involvement, has been widely demonstrated in previous reports." (PMID 36983435, 2023). "The growth differentiation factor GDF15, also called macrophage inhibitory cytokine 1, is a marker of mitochondrial disease, and is increased in both IBM and in cancers." (PMID 35806366, 2022). "In evidence, combining GDF-15 with gelsolin plasma levels performed even better to differentiate patients with mitochondrial disease than the combination with FGF-21 (AUC 0.94 vs. 0.91)." (PMID 36361969, 2022). "The IBM pathogenesis includes mitochondrial dysfunction as reflected by high levels of differential growth factor 15 (GDF15), a mitochondrial disease marker." (PMID 36189221, 2022). "A recent study quantified plasma GDF-15 in a wide variety of mitochondrial diseases, including 23 adult LHON patients." (PMID 34048486, 2021). "In a Japanese cohort aimed at studying the effect of GDF-15 on mitochondrial diseases, GDF-15 was positively correlated with age (r = 0.72, p < 0.001) in ALS patients." (PMID 34484296, 2021). "With regard to the diagnosis of mitochondrial diseases, GDF-15 seems to have an improved sensitivity and specificity in comparison to FGF-21." (PMID 34572118, 2021). "Increased blood levels of GDF15 have been observed in aging and in mitochondrial disease, and this protein has been related to cardiovascular and brain disease." (PMID 33333910, 2020). "We have subsequently compared circulating GDF15 and FGF21 levels in a cohort consisting exclusively of children with a diagnosis of mitochondrial disease which included patients with mutations in both mtDNA and nDNA." (PMID 32397676, 2020). "FGF21, GDF15, as well as VEGF and IL6, have been associated individually with a range of non-mitochondrial diseases, encompassing cancer, obesity, renal disease, diabetes, and liver disease, although many of them are characterized by an OXPHOS dysfunction." (PMID 32397676, 2020). "Later it was found that GDF15 was significantly elevated in mitochondrial disease patients, and appeared to increase with the clinical severity of the disease." (PMID 32397676, 2020).
mitochondrial disease (continued). "In order to validate the feasibility of GDF15 as a serum biomarker, its concentration was measured in the serum of 17 patients with mitochondrial diseases as well as in that of 13 patients with other pediatric diseases as a control." (PMID 32397676, 2020). "In addition, we demonstrated that GDF-15 outperformed other diagnostic biomarkers for mitochondrial diseases and postulated that it may also serve to monitor response to treatment based on preliminary data of one patient with TK2 deficiency that was treated with deoxynucleotides replacement therapy." (PMID 32572108, 2020). "Biomarkers, such as growth differentiation factor-15, were developed to assist in the diagnosis of mitochondrial diseases." (PMID 31630688, 2019). "Markedly increased circulating GDF15 values have now been reported in a variety of inherited mitochondrial diseases." (PMID 31801546, 2019). "Growth differentiation factor-15 can be used not only for the diagnosis of mitochondrial disease, but as an indicator of its acute exacerbation." (PMID 31630688, 2019). "More recently, the growth differentiation factor 15 (GDF-15), which is a member of the transforming growth factor β superfamily, is shown to be significantly higher in the serum of patients with mitochondrial disease." (PMID 30406383, 2018). "The hepatic expression of two circulating mitochondrial disease markers, Fgf2118 and Gdf1519 was up-regulated in Bcs1lG/G mice and Gdf15 expression was normalized by KD." (PMID 28424480, 2017). "Intriguingly, plasma GDF15 was recently reported to be increased in mitochondrial disease patients, which often features slowed body growth as well." (PMID 28572090, 2017). "Also, the expression of the circulating cytokines fibroblast growth factor 21 (FGF21) and growth/differentiation factor 15 (GDF15), found upregulated in various mitochondrial disease models, was significantly induced in PolɣD1135A cells." (PMID 39918244, 2025). "Interestingly, GDF15 levels in patients with late-onset MADD were three times higher than those observed in mitochondrial diseases (MDs)." (PMID 40181460, 2025). "Similarly, in a group of children with perinatally acquired human immunodeficiency virus (HIV) infections, those with mitochondrial disease had significantly higher GDF15." (PMID 40019842, 2025). "Increased levels of GDF15 in mitochondrial diseases have been confirmed in the previous studies." (PMID 40181460, 2025). "Hence, serum levels of the mitokine GDF15 are used clinically as a predictor of morbidity and mortality in people with mitochondrial diseases." (PMID 39190624, 2024). "Further, GDF15 expression is increased in cells exposed to respiratory chain inhibitors, both in animal models of mitochondrial diseases, and in the skeletal muscle of patients with mitochondrial diseases." (PMID 36978899, 2023). "Therefore, GDF-15 emerges as a promising biomarker to select which patients with fatigue should undergo further studies to exclude mitochondrial disease." (PMID 36983435, 2023). "Several reports have recently suggested that GDF-15 may be an effective marker of mitochondrial damage and thus is helpful in diagnosing mitochondrial diseases." (PMID 36927781, 2023). "Importantly, numerous studies have demonstrated elevated levels of serum FGF21 and GDF15 in patients with mitochondrial disease (MD) characterized by myopathy, but also in age-related diseases." (PMID 37941910, 2023). "Furthermore, Gdf15 is a circulating biomarker of mitochondrial disease, with its degree of expression being correlated to disease severity." (PMID 35940556, 2022). "It is important to clarify the specific function of GDF15 in mitochondrial diseases." (PMID 34445593, 2021). "The results of a more recent study clearly demonstrated a significant increase in GDF15 in the serum of individuals with mitochondrial disease, which significantly differentiated the mitochondrial DNA genetic defects group from the nuclear DNA genetic defects group." (PMID 34445593, 2021).
mitochondrial disease (continued). "Plasma GDF-15 is currently one of the most sensitive biomarkers to detect mitochondrial dysfunction, with an average sensitivity vs specificity of 89.7% to identify mitochondrial disease patients." (PMID 34048486, 2021). "To conclude, an interesting new hypothesis is that GDF15 could be used as a marker for the diagnosis of mitochondrial diseases." (PMID 34445593, 2021). "Consistent with this, reduced circulating levels of the OMM protein translocator protein 18 kDa (TSPO) and increased amounts of the mitochondrial disease marker growth/differentiation factor 15 (GDF-15) have been found in MS individuals and correlate with the severity of the disease." (PMID 33557057, 2021). "However, most of the mitochondrial disease patients with abnormal GDF-15 levels had a myopathy i.e. mitochondrial dysfunction in muscle cells." (PMID 34048486, 2021). "GDF15 levels were significantly increased in the serum of mitochondrial disease patients and could clearly distinguish mitochondrial disease patients from control patients." (PMID 32397676, 2020). "Similarly to FGF21, the reliability and efficacy of GDF15 as a biomarker of mitochondrial diseases remains to be tested in others patient cohorts." (PMID 32397676, 2020). "The utility of GDF15 in mitochondrial disease has been confirmed in several studies where GDF15 has been shown to correlate with clinical and histopathological markers of disease severity, with extent of mitochondrial heteroplasmy and with response to nucleoside therapy." (PMID 32310257, 2020). "Likewise serum FGF21, serum GDF15 seems to be a more specific marker for mitochondrial diseases due to mitochondrial translation and mtDNA maintenance defects, as opposed to those resulting from impaired respiratory chain complex or assembly factors." (PMID 32397676, 2020). "Therefore, GDF15 is potently induced by mitochondrial stress in skeletal muscle in rodent models and circulates at high levels in human mitochondrial disease." (PMID 32310257, 2020). "growth differentiation factor 15 has been cited as a possible biomarker of mitochondrial disease." (PMID 30423112, 2019). "Regardless, recent treatment advances specifically in mitochondrial diseases have shown promise in concurrently lowering GDF15 levels and mediating systemic damage, suggesting that GDF15 antagonism may provide benefit in some aspect of systemic mitochondrial disease." (PMID 40019842, 2025). "Previous adult and in vitro studies show GDF15's role as a mitokine, a soluble factor generated in response to mitochondrial stress and as such may serve in diagnosing, prognosticating and/or treating mitochondrial disease." (PMID 40019842, 2025). "Interestingly, GDF15 has been used as a biomarker for primary mitochondrial diseases." (PMID 36836688, 2023). "However, along these lines, little is known about the specific downstream effects and mode of action of GDF15 in pathophysiological relevant settings of mitochondrial stress, which is crucial to develop tailored therapeutics for patients with mitochondrial disease." (PMID 36271504, 2022). "Secondly, we showed higher plasma GDF15 in these mice which may contribute to the observed lower food intake that thus contributed to the reduced bodyweight and fat mass, as shown in other models of mitochondrial disease." (PMID 36091365, 2022). "Interestingly, the combined assessment of the serum levels of both FGF-21 and GDF-15 from adult patients with mitochondrial disease has not been found to improve the diagnostic value of the individual tests." (PMID 35806492, 2022). "Some researchers hypothesized that GDF15 might be helpful for mitochondrial diseases." (PMID 35721026, 2022). "Hence, in line with the variability of mitochondrial disease manifestations seen in patients, the here-identified mitochondrial stress-induced GDF15-GFRAL axis might be differently regulated in other mouse models of tissue-specific mitochondrial stress." (PMID 36271504, 2022).